GARIN1A (golgi associated RAB2 interactor 1A)
Description:
RAB2B effector protein required for accurate acrosome formation and normal male fertility.
Synonyms: FAM137B; FAM71F2; GARI
Tractability: No criterion of Open Targets' tractability assessment is met for any kind of drug.
Gene: Protein-coding gene on chromosome 7 (128,671,693 to 128,687,877, forward strand). Ensembl gene ENSG00000205085.
Subcellular location: Golgi apparatus
Subcellular location (Human Protein Atlas): Nucleoplasm
Gene Ontology:
Biological process: acrosome assembly
Cellular component: Golgi apparatus
Genetic constraint (gnomAD): Loss-of-function variants: 21 observed, 22.32 expected, observed/expected ratio (o/e) 0.94, 90% interval 0.67 to 1.36. The upper end of that interval is the gene's LOEUF score, 1.36, which puts it in group 5 of 6, group 1 being the genes least tolerant of losing a copy. Missense variants: 394 observed, 342.45 expected, observed/expected ratio (o/e) 1.15, 90% interval 1.06 to 1.25. Synonymous variants: 155 observed, 138.44 expected, observed/expected ratio (o/e) 1.12, 90% interval 0.98 to 1.28.
Homologues: Orthologues: chimpanzee GARIN1A (98% identical), macaque GARIN1A (95% identical), pig GARIN1A (81% identical), dog GARIN1A (80% identical), guinea pig GARIN1A (79% identical), rat Garin1a (74% identical), mouse Garin1a (73% identical), rabbit GARIN1A (67% identical). Paralogues in human: GARIN1B (52% identical), GARIN3 (23% identical), GARIN5B (21% identical), GARIN4 (19% identical), GARIN2 (19% identical), GARIN6 (17% identical), GARIN5A (16% identical).
Diseases named in the same sentence as GARIN1A in open-access papers:
GARIN1A is named in the same sentence as 5 diseases in open-access papers, as found by Europe PMC text mining. Sharing a sentence is not in itself a finding about the gene and the disease. The quoted sentences say what the papers report.
Globozoospermia (3 papers, 2024 to 2025). Any structural anomaly of the acrosome resulting in a round sperm head. "In our previous study, we identified two globozoospermia-related genes: Golgi Associated RAB2 Interactor 1A (Garin1a; Fam71f2) and Garin1b (Fam71f1)." (PMID 38935810, 2024).
Infertility (1 paper, 2024). "Garin1a and Garin1b are predominantly expressed in the testes and KO of Garin1a and Garin1b causes subfertility and infertility in males, respectively, due to abnormal acrosomal morphology." (PMID 38935810, 2024).
GARIN1A also shares sentences with these, for which no sentence is quoted: male infertility (2 papers); testis cancer (1); tumor (1).